CBFA2T2 (CBFA2/RUNX1 partner transcriptional co-repressor 2)
Description:
Transcriptional corepressor which facilitates transcriptional repression via its association with DNA-binding transcription factors and recruitment of other corepressors and histone-modifying enzymes. Via association with PRDM14 is involved in regulation of embryonic stem cell (ESC) pluripotency. Involved in primordial germ cell (PCG) formation. Stabilizes PRDM14 and OCT4 on chromatin in a homooligomerization-dependent manner (By similarity). Can repress the expression of MMP7 in a ZBTB33-dependent manner. May function as a complex with the chimeric protein RUNX1/AML1-CBFA2T1/MTG8 (AML1-MTG8/ETO fusion protein) which is produced in acute myeloid leukemia with the chromosomal translocation t(8;21). May thus be involved in the repression of AML1-dependent transcription and the induction of G-CSF/CSF3-dependent cell growth. May be a tumor suppressor gene candidate involved in myeloid tumors with the deletion of the 20q11 region. Through heteromerization with CBFA2T3/MTG16 may be involved in regulation of the proliferation and the differentiation of erythroid progenitors by repressing the expression of TAL1 target genes (By similarity). Required for the maintenance of the secretory cell lineage in the small intestine. Can inhibit Notch signaling probably by association with RBPJ and may be involved in GFI1-mediated Paneth cell differentiation (By similarity).
Synonyms: EHT; MTGR1; ZMYND3; p85
Tractability: PROTAC: UniProt records ubiquitination sites on it; ubiquitination databases record sites on it.
Gene: Protein-coding gene on chromosome 20 (33,490,075 to 33,650,036, forward strand). Ensembl gene ENSG00000078699.
Subcellular location: Nucleus
Subcellular location (Human Protein Atlas): Nuclear speckles
Pathways (Reactome):
Reproduction: Specification of primordial germ cells
Gene Ontology:
Molecular function: protein binding; transcription corepressor activity
Biological process: negative regulation of DNA-templated transcription; positive regulation of neuron projection development; negative regulation of neuron projection development; DNA-templated transcription; intestinal epithelial cell differentiation; negative regulation of Notch signaling pathway
Cellular component: nucleus; nucleoplasm
Genetic constraint (gnomAD): Loss-of-function variants: 9 observed, 49.94 expected, observed/expected ratio (o/e) 0.18, 90% interval 0.11 to 0.31. The upper end of that interval is the gene's LOEUF score, 0.31, which puts it in group 1 of 6, group 1 being the genes least tolerant of losing a copy. Missense variants: 520 observed, 706.12 expected, observed/expected ratio (o/e) 0.74, 90% interval 0.68 to 0.79. Synonymous variants: 262 observed, 271.73 expected, observed/expected ratio (o/e) 0.96, 90% interval 0.87 to 1.07.
Homologues: Orthologues: chimpanzee CBFA2T2 (98% identical), macaque CBFA2T2 (98% identical), pig CBFA2T2 (97% identical), mouse Cbfa2t2 (96% identical), guinea pig CBFA2T2 (96% identical), dog CBFA2T2 (96% identical), rat Cbfa2t2 (95% identical), rabbit CBFA2T2 (95% identical), tropical clawed frog cbfa2t2 (78% identical), zebrafish cbfa2t2 (65% identical), Drosophila melanogaster nvy (30% identical). Paralogues in human: RUNX1T1 (63% identical), CBFA2T3 (58% identical).
Diseases named in the same sentence as CBFA2T2 in open-access papers:
CBFA2T2 is named in the same sentence as 16 diseases in open-access papers, as found by Europe PMC text mining. Sharing a sentence is not in itself a finding about the gene and the disease. The quoted sentences say what the papers report.
bladder cancer (3 papers, 2020 to 2021). "Lastly, circ_0008532 (gene of origin: CBFA2T2) affects bladder cancer progression by increasing the levels of the mRNA encoded by its parental gene, through miR-155-5p and miR-330-5p sponging." (PMID 34205978, 2021). "CBFA2T2 (MTGR1) acts as a Notch signaling suppressor and, in this case, Notch-mediated signaling repression leads to the reinforcement of the migratory and invasive capabilities of bladder cancer cells." (PMID 34205978, 2021).
renal cell carcinoma (3 papers, 2017 to 2020). "CBFA2T2 (also known as MTGR1), a member of the Myeloid Translocation Gene (MTG) family of transcriptional corepressors, can significantly predict the survival of renal cell carcinoma (RCC) patients." (PMID 32913470, 2020).
acute myeloid leukemia (2 papers, 2017 to 2024). Acute myeloid leukemia (AML) is a group of neoplasms arising from precursor cells committed to the myeloid cell-line differentiation. "CBFA2T2 has been known as a fusion partner of RUNX1 in acute myeloid leukemia, suggesting a role of CBFA2T2 in cancer development." (PMID 29162985, 2017). "In acute myeloid leukemia, CBFA2T2 has been identified as a fusion partner of RUNX1." (PMID 29162985, 2017). "MTGR1 (Cbfa2t2) is a member of the three-protein myeloid translocation gene (MTG) family of transcriptional co-repressors, which were originally identified in translocation fusion proteins driving acute myeloid leukemia." (PMID 39048708, 2024). "Interestingly, fusion RUNX1/CBFA2T2 transcript is highly upregulated compared with wild-type CBFA2T2 gene, suggesting that CBFA2T2 alone might not be sufficient for the development of acute myeloid leukemia." (PMID 29162985, 2017).
leukemia (2 papers, 2012 to 2022). A malignant (clonal) hematologic disorder, involving hematopoietic stem cells and characterized by the presence of primitive or atypical myeloid or lymphoid cells in the bone marrow and the blood. "Notably, the ETO-family transcriptional corepressors, including ETO (also known as RUNX1T1), ETO2 (also known as CBFA2T3) and MTGR1 (also known as CBFA2T2), are all involved in leukemia-causing chromosomal translocations." (PMID 36158200, 2022).
medulloblastoma (2 papers, 2023 to 2025). A malignant, invasive embryonal neoplasm arising from the cerebellum. "CBFA2T2 and CBFA2T3 are recurrently mutated in Group 4 medulloblastoma, a tumour hypothesized to originate in the rhombic lip subventricular zone." (PMID 41279093, 2025). "Mutually exclusive mutations in group 4 medulloblastomas could be attributed to the effect of the core binding factor (CBFA) and include CBFA2T2, CBFA2T3, PRDM6, UTX, and OTX2 genes." (PMID 36829544, 2023). "These include enhancers of regulators of genes that drive glutamatergic neuronal identity (e.g., PAX6, WLS), and known drivers of medulloblastoma (OTX2, MYCN, CBFA2T2)." (PMID 41279093, 2025). "Notably, 37 of the superenhancers had known Group 3 and 4 medulloblastoma drivers as their nearest genes, including CHD7, CBFA2T2, GSE1, and of course, OTX2, and ZIC1." (PMID 41279093, 2025).
breast carcinoma (1 paper, 2020). "As α2M and CBFA2T2 showed relatively high expression, whilst AHSG and hornerin showed extremely low expression in MDA-MB-231 and MDA-MB-468 cells, we speculated that α2M and CBFA2T2 may play key roles in GALNT6-mediated metastasis of breast cancer." (PMID 32559179, 2020).
Sepsis (1 paper, 2023). Sepsis is defined as life-threatening organ dysfunction caused by a dysregulated host response to infection. "GO analysis of the DE RBPs in sepsis identified terms that were mostly enriched in the immune/inflammatory response; we identified significant differences in 8 down-regulated RBPs in sepsis, including DDX24, CBFA2T2, NOP, ILF3, DNMT1, FTO, PPRC1, NOLC1." (PMID 37749550, 2023). "Thus, the expression levels of the eight RBPs (DDX24, CBFA2T2, NOP14, ILF3, DNMT1, FTO, PPRC1, and NOLC1) were altered in the patients with sepsis might potentially be useful as novel biomarkers as well as targets to facilitate the diagnosis and management of sepsis." (PMID 37749550, 2023).
cancer (6 papers, 2012 to 2025). A tumor composed of atypical neoplastic, often pleomorphic cells that invade other tissues. "CBFA2T2 expression is necessary for sphere-forming ability and cancer stem cells marker expression in RCC cell lines." (PMID 29162985, 2017). "Importantly, CBFA2T2 is required for sphere-forming ability and cancer stem cells marker expression in RCC cell lines." (PMID 29162985, 2017). "Indeed, our immunohistochemistry staining showed elevated expression of CBFA2T2 in RCC cancer compared to normal kidney tissue." (PMID 29162985, 2017). "This further supports that CBFA2T2 is required for maintenance of cancer stem cell property in RCC." (PMID 29162985, 2017). "To investigate whether CBFA2T2 play a role in RCC cancer development, we used siRNA to inhibit CBFA2T2 expression." (PMID 29162985, 2017). "Knocking-down of CBFA2T2 can inhibit cell migration and invasion in RCC cells in vitro, and reduce ALDH high cancer stem cells (CSCs) populations." (PMID 32913470, 2020).
CBFA2T2 also shares sentences with these, for which no sentence is quoted: colitis (2 papers); acute leukemia (1); colorectal cancer (1); Familial adenomatous polyposis (1); infection (1); renal carcinoma (1); tauopathy (1); tumour (1).